RB1 (RB transcriptional corepressor 1)
Diseases named in the same sentence as RB1 in open-access papers (continued):
Sharing a sentence is not in itself a finding about the gene and the disease.
tumor (continued). "Tumor RB1 mutation status was determined using an FDA‐cleared tumor sequencing assay, MSK‐IMPACT." (PMID 32633890, 2020). "Indeed, RB1 is mainly mutated or deleted across many forms of cancer, which is consistent with its role as a tumor suppressor." (PMID 33266490, 2020). "In the context of RB1, there is frequent single copy loss along 13q in many tumor types." (PMID 32242058, 2020). "RB1 is a tumor suppressor that is frequently mutated in VN-MCC tumors." (PMID 32344701, 2020). "In addition, the presence of acquired mutations in RB1, identified in circulating tumor DNA (ctDNA), has also been associated to clinical resistance in BC patients treated with CDK4/6i." (PMID 32899866, 2020). "Moreover, the candidate gene list drew attention to Rb1 (also known as Rb) that encodes the retinoblastoma-associated protein, a key regulator of cell cycle entry as well as cellular division, and a tumor suppressor." (PMID 32164318, 2020). "Interestingly, SKP2 molecules are sustained by TRβ2 that antagonizes the tumor-suppressive function of TRβ1 to promote development of RB1-deficient malignancies." (PMID 32824373, 2020). "The presence of a stopgain mutation (p.W563*) in RB1 (which encodes retinoblastoma protein) suggests that this tumor suppressor may be functionally inactivated in the CtxR 4 cells." (PMID 31914141, 2020). "Based on the emerging evidence that pRb directly regulates metabolism, we hypothesized that the loss of Rb1 promotes a metabolic phenotype that supports tumor progression." (PMID 31963621, 2020). "Patients with RB1 loss in the primary tumor had a worse prognosis." (PMID 31874108, 2020). "Additionally, RB1 deficiency is able to enhance tumor metastasis by increasing OXPHOS to generate more ATP fueling for tumor invasion and cooperating oncogenic alterations to uphold EMT and metastasis." (PMID 33489906, 2020). "Its inactivation in addition to RB1 loss could avoid excessive cell proliferation, which could be deleterious for tumor development in terms of nutrient and energy expenditure for example but also in terms of response to treatment." (PMID 30641971, 2019). "While the initiation of tumorigenesis in RB begins with a mutation in the RB1 tumor suppressor gene, additional genetic and genomic arrangements may be required for continued tumor growth." (PMID 31835688, 2019). "Both alleles of the RB1 gene must be mutated for tumour development." (PMID 30745306, 2019). "RB1, a tumor suppressor and well-known cell cycle regulator, has mutations in Rb." (PMID 31614829, 2019). "Deep sequencing of the two fins and CrispRVariants-based allele analysis validated that the tumor contained two independent frameshift mutations in rb1 at the protospacer adjacent motif site that are characteristic of CRISPR mutations and were not present in the control tail fin." (PMID 30061297, 2018). "Tumor tissues harboring ATM/RB1 mutations may have increased mutation rates due to DNA repair defect." (PMID 29682192, 2018). "In addition, cone-associated genes that are susceptible to RB transformation were enriched in tumor and organoids, in response to RB1 inactivation." (PMID 30353124, 2018). "While two tumor suppressor genes, RB1 and FOXO1, are encoded in this region, the precise molecular pathogenesis of these tumors is unknown." (PMID 28887603, 2018). "For example, Rb1 (retinoblastoma-associated protein) is a tumor suppressor inhibiting cell cycle progression, which may also recruit methylases." (PMID 29653584, 2018).
tumor (continued). "Further study should be undertaken to evaluate whether RB1 loss is a recurring feature in this histology and whether platinum-based chemotherapy is more broadly effective in this tumor type outside of this case." (PMID 28390395, 2017). "Given this mounting evidence, we hypothesize that RB1 mutation in our patient’s tumor predisposed to chemosensitivity." (PMID 28390395, 2017). "Since RB1 loss is frequently observed in CRPC, the RB1/E2F-1 complex could play a significant role in tumor progression." (PMID 28264478, 2017). "List of somatic RB1 point mutation identified only in tumor cells." (PMID 28575107, 2017). "All but one bilateral tumor presented with germline RB1 mutations (17/18; 94.4%)." (PMID 28575107, 2017). "Mutations in RB1 correlated with the same group of gene dysregulations across several tumour types." (PMID 26436532, 2015). "Thus, mutation or inactivation of the Rb1 pathway, which is a hallmark of cancers, is critical for Ras-initiated tumor formation." (PMID 25880398, 2015). "This suggests bi-allelic loss of RB1 specifically in the SCLC transformed tumours." (PMID 25758528, 2015). "Therefore, RB1 phosphorylation mutants and truncated variants that remain in the hypophosphorylated status have been used in preclinical models to enhance RB1 tumor suppressor function." (PMID 26160835, 2015). "Finally, RB1 mutants were noted to have smaller T2-FLAIR hyperintensity and total tumor volumes but similar contrast enhancing and necrosis volumes compared to wild-type tumors, demonstrating the effect of RB1 on tumor-associated T2-FLAIR hyperintensity." (PMID 26337765, 2015). "Despite these findings, the influence of Rb1 loss-of-function on female germ cell development and tumor formation remains unclear." (PMID 26176933, 2015). "Thus, cell lines derived from cancers that either have transformed into SCLC or derived from tumours prone to transform into SCLC both demonstrated genetic loss of RB1." (PMID 25758528, 2015). "The associations between the mutations in RB1 and age at diagnosis or tumor stage were analyzed." (PMID 25602518, 2015). "Moreover, other oncolytic viruses were designed to exploit the deregulated E2F transcriptional activity resulting from RB1 loss for their replication and tumor cell killing." (PMID 26160835, 2015). "The first aims to take advantage of RB1 loss mainly through the research of synthetic lethal interactions and the use of oncolytic viruses, which depend on RB1 inactivation for their replication and tumor cell killing." (PMID 26160835, 2015). "The spatiotemporal distribution of tumor locations likely reflects regional developmental events in the young retina that facilitate cell survival and proliferation after the requisite inactivating mutation in RB1 is acquired." (PMID 26230335, 2015). "Interestingly, in other tumors p27 loss desensitizes Rb1 null tumor cells to Arf-mediated apoptosis." (PMID 24274149, 2013).
tumor (continued). "We hypothesized that Rb1 plays a critical role in tumor initiation, but instead identified Rb1 loss as a disease modifier resulting in not only anaplasia but also a switch from aRMS to pleomorphic RMS identity." (PMID 24274149, 2013). "The final cell cycle heterogeneity may present a cellular context that is more permissive to tumour development when Rb1 is mutated." (PMID 23527113, 2013). "The unique sensitivity of developing retina to RB1 loss may be explained by an inability to trigger protective tumor suppressor pathways readily activated in other tissues." (PMID 22336108, 2012). "Hence, various researchers are trying to develop novel anti-tumor agents with selective anti-tumor effects on RB1-deficient tumors, or find RB1 context specificity for current standard-of-care medicines." (PMID 21447152, 2011). "Likewise, the chromosome 13 loss, associated with RB1 loss occurs in all human and mouse tumor groups, and all overlapping regions encompass the INTS6 gene." (PMID 20735817, 2010). "Lastly, the p16INK4a expression seen in DCIS by Gauthier and colleagues, and the elevated Ki-67 index seen in basal-like DCIS lesions, suggests that RB1 loss may be an early event for this tumour type." (PMID 18782450, 2008). "Basal-like tumours also highly express a recently published RB-loss gene expression signature, which we have shown to have significant similarity to a previously defined proliferation signature and our newly described RB1 LOH signature." (PMID 18782450, 2008). "In addition to direct mutation of the RB-1 gene, its encoded protein (pRB) is functionally inactivated in many tumor cells either by viral proteins that bind to pRB, or through changes in a regulatory pathway that controls the activity of pRB." (PMID 18834508, 2008). "The retinoblastoma susceptibility gene (RB-1) was the first tumor suppressor gene to be cloned." (PMID 17854503, 2007). "Germline mutations in specific codons or regions of the RB1 gene could therefore predispose to the development of a second tumour." (PMID 16685266, 2006). "The gene RB1, encoding the protein, was mapped to chromosome 13q14.12–13q14.2 in children who developed retinoblastoma, a rare cancer of the eye, and was the first tumour-suppressor gene to be cloned." (PMID 16685266, 2006). "The inactivation of both RB1 alleles in tumour cells was initially detected in association with LOH at the RB1 locus on chromosome 13, and microdeletions or inactivating mutations in the retained allele would be responsible for complete inactivation of the gene." (PMID 12556968, 2003). "Loss of the RB1 gene is an important event in the initiation and progression of many tumours." (PMID 7526887, 1994). "Our findings that RB1 loss shifts the primary carbon source from glucose to glutamine via PGAM downregulation in 53KOLS cells highlight thus far an unknown mode of metabolic adaptation that supports tumor growth under metabolic stress." (PMID 40707487, 2025).
tumor (continued). "Targeted NGS analysis of AH samples collected from treatment-naive primary enucleated eyes (PE) determined that our capture-based NGS assay could detect 94% of RB1 pathogenic variants previously identified by clinical testing of the paired genomic and/or tumour DNA." (PMID 38672657, 2024). "This human tumor model, based on iPSCs derived from patients with germline mutations predisposing to cancer, could contribute to understand the cellular origin of this disease and the mechanisms of tumorigenesis following RB1 gene inactivation." (PMID 38835365, 2024). "Additionally, exploring the tumor microenvironment’s role in modulating the effects of RB1 deficiency and identifying potential therapeutic targets within the tumor stroma could open up new avenues for treatment." (PMID 38672640, 2024). "However, it is unclear whether a similar epigenetic model is occurred in RB1-mutational tumor cells, and it would be of great interest to further explore the epigenetic possibility of RB1 activation in RB1-mutational tumor cells." (PMID 36175480, 2022). "Second, the novel ability to characterize tumor-specific somatic mutations in vivo, at diagnosis, creates opportunity for larger, prospective studies investigating the prognostic value of specific somatic RB1 alterations or other pathogenic mutations, such as BCOR or CREBBP." (PMID 33805776, 2021). "However, the failure to identify mutations of both copies of RB1 in a proportion of Rb tumours led to speculation that other genes may be involved with alternative pathways to malignancy." (PMID 33670346, 2021). "Indeed, in approximately 2% of tumours, RB1 mutations are elusive." (PMID 33670346, 2021). "Interestingly, previous studies have linked RB1 loss to tumor progression." (PMID 33831375, 2021). "Moreover, an RB1 gene mutation has been found in the OS-33 PDX tumor in this study." (PMID 32676162, 2020). "Similarly, the RB1 gene is mutated in a variety of human cancers and represents a classical prototype of tumor suppressor, inhibiting cell proliferation primarily through targeting of the E2F transcription factor and, additionally, through transcription-independent mechanisms." (PMID 31616639, 2019). "Besides this mechanism, loss of RB1 also results in tumour formation and progression." (PMID 30258198, 2018). "It was surprising that the allelic fraction of rb1 mutations was low in our MiSeq analysis, but this could be due to the fact that, in isolating genomic DNA for sequencing, we included large margins of surrounding normal tissue along with the tumor." (PMID 30061297, 2018). "Given increasing evidence suggesting RB1 loss is associated with responsiveness to conventional chemotherapies, particularly platinum-based regimens, we hypothesize that this genetic feature predisposed chemosensitivity in our patient’s tumor." (PMID 28390395, 2017).
tumor (continued). "Thus, to explore whether loss of RB1 had occurred after integration of MCPyV during tumor progression, we analyzed a metastasis excised at the time when the cell line LoKe was established and the primary tumor excised 3 years before." (PMID 27121059, 2016). "Similarly, an early evolutionary history of the second tumour (OS-059) could have been driven either by a germline MUTYH mutation or by a somatic RB1 mutation." (PMID 26632267, 2015). "These genetic and epigenetic events occur within limited spatiotemporal intervals during retinal maturation, and therefore the complex spatiotemporal pattern of tumor occurrence may help to identify critical events that cause malignant transformation of retinoblasts with inactivating RB1 mutations." (PMID 26230335, 2015). "A functional loss of Rb1 has been described to cause a positive feedback loop with p16 leading to accumulation of the protein (hence, immunohistochemical overexpression) without ability to halt the cell cycle; essentially negating its “tumor suppressor” ability." (PMID 24752337, 2014). "Therefore, loss of RB1 function via mislocalization may disrupt normal cell differentiation processes and promote tumor progression." (PMID 23233783, 2012). "In addition to the deregulated expression of metabolism associated genes, we noticed that among the DEGs in the hepatocarcinogenesis of rat models, some known tumor-associated genes, such as Rb1 and Myc, showed deregulated expression occurring at all the stages of hepatocarcinogenesis." (PMID 19638242, 2009). "We might thus consider that most cases with hypermethylated RB1 promoter in our series most probably would show loss of pRB expression, although we had no possibility to perform pRB expression studies in our series of tumours to demonstrate this." (PMID 12556968, 2003). "Morphologically, RB1−/− ROs lost laminated structure, comprised homogenous tumor-like cells with a larger nuclear size and mitotic figures." (PMID 41535675, 2026). "RB1 is a crucial tumor suppressor that regulates the progression of the cell cycle by inhibiting the transition from the G1 phase to the S phase." (PMID 40491286, 2026). "In this context, CDK4/6 inhibitors can restore RB1 activity, re-establishing cell-cycle arrest and reducing tumor growth, as demonstrated in RB1-dependent MPNST models." (PMID 41463204, 2025). "Low RB1 expression not only contributes to tumour initiation and progression but also leads to resistance to various drug therapies." (PMID 40070134, 2025). "The discovery of RB1 made a revolution in oncology because this changed the conception of tumor genetics." (PMID 40227591, 2025). "Biallelic inactivation of RB1, either germline or somatic, is necessary for tumor development, especially in heritable and bilateral cases." (PMID 41009976, 2025). "Second, we extended the RB1-defective group by including additional 34 tumor samples harboring either an RB1 deep deletion or RB1 truncating mutation (MT)." (PMID 40138429, 2025).